ERBB2 (erb-b2 receptor tyrosine kinase 2)
Diseases named in the same sentence as ERBB2 in open-access papers (continued):
Sharing a sentence is not in itself a finding about the gene and the disease.
tumor (continued). "These tumour subtypes are primarily recognized by expression of three cellular receptors, (a) estrogen receptor (ER, HGNC gene symbol ESR1), (b) progesterone receptor (PR, HGNC gene symbol PGR) and (c) the epidermal growth factor receptor family member Her2/Neu (HGNC gene symbol ERBB2)." (PMID 26553005, 2015). "These other receptors could influence the absence of positive correlations between ERBB2 and the phospho-proteins in tumor cells." (PMID 25853295, 2015). "Additionally, SN-38 treatment did not reduce the ErbB2-KD xenografts tumor volume as previously observed on NT xenografts." (PMID 25890497, 2015). "A total of 357 (tumour) and 222 (non-malignant basal and luminal) cases were scored for ErbB2-IR." (PMID 25215939, 2014). "One reason for the rather minor effects of TKI on local tumour control could be that through heterodimerisation with other receptors of the EGFR-family, e.g. ErbB2, signaltransduction is still possible and therefore exclusively blocking the EGFR-TK is not sufficient." (PMID 25444177, 2014). "Therefore, it seems that SOX9 and c-myc might play more dominant roles than ERBB2 and WNT3 in determining tumor stemness in this tumor model." (PMID 25003837, 2014). "From the previous results presented in this paper, Ki67 is an obvious confounder, and a Bivariate Cox proportional hazards regression analyses indicated that the tumour ErbB2-IR did not provide additional prognostic information to that provided by either the tumour Ki67 index." (PMID 25215939, 2014). "However, a Bivariate Cox proportional hazards regression analyses controlling for Gleason score (three groups: 4–6, 7 and 8–10) indicated that the prognostic value of tumour ErbB2-IR no longer remained significant." (PMID 25215939, 2014). "Several molecular mechanisms are involved in the resistance to anoikis of tumor cells, including survival signaling driven by PI3K and NF-κB pathways, the expression of anti-apoptotic proteins such as Bcl-2, and the hyperactivation of tyrosine kinase receptors such as EGFR and ErbB2." (PMID 25788857, 2014). "The left-handed cluster (purple bar) includes the non-basal tumours (luminal and ErbB2+)." (PMID 23555842, 2013). "Finally, ErbB2-KD and MUC4-KD cells showed impaired tumour growth in vivo." (PMID 22393391, 2012). "This feature might partly explain why pertuzumab inhibits the growth of tumours that express low ErbB2 levels, whereas trastuzumab does not." (PMID 23202898, 2012). "To assess whether loss of polarity protein-induced invasion is relevant in contexts other than ErbB2 activation in MCF-10A cells, we used a non-invasive tumor derived human cell line, MCF-7, and xenograft-selected MCF10AT displaying comedo-type Ductal-Carcinoma-In-Situ phenotype (DCIS.COM) cells." (PMID 22529912, 2012). "TMAs from 226 tumor samples from our cohort were analyzed for MembErbB-2 expression by IHC using the rabbit monoclonal antibody RBT-HER2 and the rabbit polyclonal antibody A0485, which was approved by the Food and Drug Administration (FDA) and is routinely used for ErbB-2 evaluation." (PMID 22356700, 2012). "We also show that they play roles in different properties of cancer cells with ErbB2 clearly affecting proliferation, cell cycle and tumour growth whereas MUC4 shows a wider spectrum of activities ranging from proliferation, cell cycle, tumour growth but also migration and invasion." (PMID 22393391, 2012). "Consistent with the literature, our data could also suggest that Notch plays a critical role in the survival of tumour-initiating cells as demonstrated by the lack of tumour recurrence when Notch was inhibited in combination with ErbB-2 inhibition." (PMID 21847123, 2011).
tumor (continued). "Tumor subtypes are primarily categorized by expression of three cellular receptors: estrogen receptor (ER, HGNC gene symbol ESR1), progesterone receptor (PR, HGNC gene symbol PGR), and the epidermal growth factor receptor family member Her2/Neu (HGNC gene symbol ERBB2)." (PMID 21510869, 2011). "In univariate analysis, high ERCG4 expression (HR = 0.84 [0.76-0.92]; p = 0.0002), as well as age superior to 50 years, node-negative status, small tumor size (pT1), low grade (SBR 1), positive ER and PR status, and negative ERBB2 status, were associated with a better DFS." (PMID 22110708, 2011). "In addition to the “IBC-like” or “nIBC-like” profile, we tested the variables most frequently annotated in the six data sets: patients' age, pathological tumor size, axillary lymph node status, and grade, and IHC ER and PR status (ERBB2 status not available)." (PMID 21339811, 2011). "Similarly, when human ErbB2 tolerant mice are vaccinated with HuHuT plasmid, the growth of human ErbB2+ transplantable human (but not rat) ErbB2+ tumor is impaired." (PMID 24212954, 2011). "We show that CL4 binds EGFR on tumor cell surface as well as the soluble extracellular domain of the receptor with a Kd of 10 nM, while it does not bind to the other members of the ErbB family, ErbB2, ErbB3 or ErbB4." (PMID 21915281, 2011). "This strategy also presents one limitation, however; by using anti-EpCAM and anti-ErbB2 Micro Beads for immunoselection, tumour cells that do not express or express low levels of EpCam or HER2 may not be enriched." (PMID 21672237, 2011). "If BCAR4-positive tumours are driven by ERBB2 signalling, in the absence of gene amplification or overexpression, as our results suggest, then more patients may benefit from ERBB2-directed therapy." (PMID 20859285, 2010). "The nonluminal, HER2-positive tumours are the equivalent of the ERBB2-overexpressing tumours." (PMID 20520800, 2010). "Conventional markers for prognostication or treatment prediction or both include tumor size and lymph-node involvement, histologic grade, estrogen (ER) and progesterone receptor (PgR) expression, as well as human epidermal growth factor receptor 2 (HER2, HER2/neu, ERBB2) amplification status." (PMID 20576095, 2010). "Our studies suggest that tumours that overexpress ErbB2 which activate Akt by means of mutating PI3K, PTEN or Akt (rather than via ErbB2/ErbB3 activation of PI3K) may be resistant to ErbB2-targeted therapies." (PMID 18700973, 2008). "Also the ERBB2 gene expression level was significantly lower in the NE tumour cell group than in the non-NET group." (PMID 18827820, 2008). "Both groups used activated ErbB2 models of tumourigenesis in Akt1-/- and Akt+/+ backgrounds and demonstrated the importance of Akt1 in mediating ErbB2-induced tumourigenesis: mice lacking Akt1 either failed to develop tumours or tumourigenesis was delayed." (PMID 18700973, 2008). "However, while Akt1 is required for efficient tumour formation in MMTV-ErbB2 mouse models, activation of Akt1 alone is not sufficient for mammary tumourigenesis indicating that other pathways downstream of ErbB2 activation are important for tumour formation." (PMID 18700973, 2008). "In conclusion, ‘ERBB2 dependence’ is not sufficient to define trastuzumab-responsive tumours." (PMID 18454161, 2008). "Trastuzumab in tumours not (over)expressing ERBB2 is known to be useless." (PMID 18454161, 2008). "Finally, IHC data for EGFR and/or ErbB2 overexpression were correlated with tumour phenotype (IBC/non-IBC), ER status and the presence of transcriptionally active NF-κB dimers." (PMID 17700572, 2007).
tumor (continued). "The six different transcriptome clusters showed no significant bias with respect to tumor PR status and ERBB2 status; in contrast, two of the clusters were composed primarily of younger cases (64% of group 1A, 81% of group 2B) and one was composed primarily of older cases (68% of group 2A)." (PMID 17850661, 2007). "As a tumour antigen, here we have used human ErbB2, which is a foreign antigen in this system despite a high degree of sequence identity with its murine counterpart and the fact that Renca-lacZ/ErbB2 cells are not rejected in naïve immunocompetent animals." (PMID 15812545, 2005). "In addition to the tumour-free mice, one animal in each group that had received ErbB2 vaccines developed only small tumours and therefore did not have to be killed before the end of the experiment." (PMID 15812545, 2005). "Specifically, the growth of cell lines derived from mouse tumours arising from activated ErbB2 or from ErbB3 ligand overexpression was inhibited by Kek1 expression, while the growth of a cell line derived from a tumour arising from activated ras was not inhibited." (PMID 14735165, 2004). "Furthermore, mIHC analysis confirmed that AREG and EGFR/ERBB2, as well as NAMPT and ITGA5/ITGB1, were overexpressed in the PMC_P region, verified in clinical specimen suggesting that these LRPs play a critical role in mediating tumor initiation in the tipping point." (PMID 40976783, 2025). "The addition of i14e vivo-MO targeting the 5SpS alone did not have inhibitory effects on tumor; but notably, the combination of early treated T-DXd with i14e vivo-MO gave rise to more therapeutic effects on tumors than that with control vivo-MO in ERBB2 positive GBC cases." (PMID 39948369, 2025). "Notably, several mutations (5× BRCA2, 4× ERBB2, 2× NRAS, 2× HCN1 [hyperpolarization-activated cyclic nucleotide-gated potassium channel 1]) were detected more than once in plasma or stool samples across all patients but never in tumor biopsies." (PMID 38766867, 2024). "Human epidermal growth factor receptor 2 (also known as ERBB2) is a membrane protein tyrosine kinase receptor and overexpression of the HER2 gene could lead to worse prognosis by affecting cell proliferation, migration, survival, angiogenesis, tumor invasion, and metastasis." (PMID 37794050, 2023). "ERBB2 amplification was detected in the CGH study for SEC1, SEC2 (both the primary tumor and metastasis) and SEC3 (only in metastasis), while the IHC analysis of different tumor regions reflects the ITGH in the patient and could reveal new targets for available treatments." (PMID 35145232, 2022). "Finally, in TKKK, the EGFR amplification could not be confirmed on the protein level, while the ERBB2 amplification clearly prevailed in tumor biology in this case." (PMID 36013219, 2022). "Moreover, despite the absence of amplifications, the existence of ERBB2 mutations and increased protein levels, indicate that ERBB2 inhibitors may be an alternative therapeutic approach for LAR subtype tumours." (PMID 36077812, 2022). "Notably, ERBB2 amplification could be identified non only in tissues but also in circulating tumor DNA of CRC patients non-responsive to anti-EGFR therapy." (PMID 35582524, 2022). "However, ECD KD resulted in increased levels of herstatin, which acts as a tumor suppressor by effectively blocking HER2 activity and cell proliferation while promoting apoptosis, supporting the notion that ECD is an important player in ErbB2-mediated oncogenesis." (PMID 33941617, 2021). "Poor-quality tumour DNA precluded assessment of ERBB3 mutation(s) in our family, noting that somatic mutations were not identified in the single family with the germline ERBB2 mutation and NSCLC and inconsistently in individuals and families with EGFR/ERBB1 mutations." (PMID 34274969, 2021).
tumor (continued). "Additionally, among the 53 drugs approved based on a new mechanism of action, regardless of the tumor type, 50 distinct biological targets were identified, with 4 having already approved drugs before 2009 (ERBB2, CD20, the cell cycle for chemotherapy, and vascular endothelial growth factor [VEGF])." (PMID 34905002, 2021). "However, tumor VEGFA mRNA and MET did have a 2.5±2.67-fold and 3.02±2.16-fold increase in comparing to that in the normal tissue in the patients, while the expression of ERBB2 mRNA showed a slightly decrease in the tumor vs non-tumor tissue (0.93±0.69-fold change)." (PMID 34335943, 2021). "Moreover, higher pCR in patients with elevated expression of ERBB2, KRT20 or ESR1 may support previous studies showing a lower cancer-specific and relapse-free survival of MIBC patients with high ESR1-expressing tumours." (PMID 34073233, 2021). "Besides, the EDF genes within subtype 1 were enriched in functions of cell growth, such as "ERBB2 signaling pathway" and "Constitutive Signaling by Aberrant PI3K in Cancer", which could affect tumor cell growth, proliferation, and migration by perturbing the PI3K/AKT/mTOR signaling pathway." (PMID 33078899, 2020). "Additionally, the ERBB2-CAR-T cell infusions for NSCLC patients showed 23.5% (4/17) SD for 12 weeks to 14 months; 17.7% (3/17) patients underwent surgical resection of their residual tumors, and one of these patients showed ≥ 90% tumor necrosis (ClinicalTrials.gov identifier: NCT00902044)." (PMID 32708604, 2020). "We show that ErbB2+ tumors that include but are not limited to ovary, colon or pancreas could benefit from treatments with the ADC ST8176AA1 that, by inducing epigenetic modulation through trastuzumab-mediated delivery of an HDACi, can inhibit tumor cell growth." (PMID 32039017, 2019). "However, as opposed to tumor cells, cardiac ErbB2 signaling is critically ligand (NRG-1)-dependent." (PMID 27596216, 2016). "However, we could detect only erbB3-derived, and not erbB2-derived, tyrosine-phosphorylated peptides in the majority of PyMT tumours." (PMID 25200860, 2014). "Despite the limited number of patients examined in this study, the significant positive correlation we observed between MBP-1 and HDAC1 expression in ErbB2-negative IDC suggests that their concomitant high expression may have a stronger diagnostic and prognostic significance in this tumor subtype." (PMID 23421821, 2013). "Thus a powerful immune response against not-tolerate epitopes of a xenogeneic (rat) ErbB2 protein could be mistaken for an anti-tumor response." (PMID 24212954, 2011). "Indeed, ErbB2 has been identified as an oncogene, and anti-ErbB2 antibody has been used as an anti-tumor drug, although ErbB3 is not identified as an oncogene because it may lack enzyme activity." (PMID 22216327, 2011). "Consequently, anti-ErbB2 antibodies were not involved in tumour rejection." (PMID 15812545, 2005). "Strikingly, treatment with an ERBB2 inhibitor drastically reduced the formation of liver metastasis, whereas ERBB2 knock-out in vitro did not affect SCLC tumor cell proliferation." (PMID 41361170, 2025). "HER2+ was reported for three tumors: an IHC 3+ tumor harboring ERBB2 V777L with ERBB2 co-amplification, an IHC 3+ tumor with D769Y + G776V and co-amplification, and an IHC 2+/FISH+ tumor with an Ex19Del (L755_T759del) which was non-amplified." (PMID 40178042, 2025).
tumor (continued). "Using ERBB2 copy number analysis by NGS, another study of 20 BCBM patients with matched primary tumor and brain resections reported that ERBB2 alterations were acquired in 20% of HER2-negative cases." (PMID 41149070, 2025). "Moreover, low tumor mitotic activity was associated with better prognosis in LUAD subgroups with EGFR mutations or pan-negative (no oncogenic alteration in genes including KRAS, EGFR, BRAF, ERBB2, PIK3CA, ALK, and ROS1) but not in those with KRAS or BRAF mutations." (PMID 41404730, 2025). "The presence of HER2-negative area in 10% of the cases by FISH or the detection of ERBB2 amplification between 5% and 50% of tumor cells defined HER2 heterogeneity." (PMID 39050884, 2024). "However, one mutation (ERBB2) found in both plasma and stool and another mutation (KCNA5 (potassium voltage-gated channel subfamily A member 5)) observed only in stool could not be detected in the resected tumor tissue." (PMID 38766867, 2024). "Comprehensive single-cell profiling of ERBB2-amplified and -non-amplified cells within the same HER2-HET tumor would be required to understand the source of this compensatory mechanism." (PMID 38300710, 2024). "No tumor DNA was detected in plasma; however, EGFR L858R and ERBB2 amplification (copy number 21.36) were found in tumor tissue." (PMID 38920723, 2024). "Manual inspection of ERBB2 in IGV using BAM files showed some coverage difference between control and tumor samples but did not reveal any strong signs of duplication." (PMID 39696035, 2024). "This entity presents as basal appearing tumor with triple-negative (ER/PR are negative and ERBB2/Her2 is not amplified) phenotype and established immune expression." (PMID 38015260, 2024). "HER2-low tumors harbored almost no ERBB2 amplification and expressed HER2 protein in the tumor cell membrane by several mechanisms, including estrogen receptor pathways, the NF-kB pathway activated by chemoradiotherapy and epigenetic changes." (PMID 37264417, 2023). "Brouwer and colleagues found that while HER2-high-expressing tumor cells demonstrated ERBB2 amplification, CTCs with negative or intermediate HER2 expression were copy-number neutral." (PMID 40028485, 2023). "The time-matched cfDNA showed a positive ERBB2 CNV value very close to the cut-off, suggesting that the solid biopsy was not representative of the whole tumor genetics." (PMID 35565309, 2022). "It is likely that the lack of inhibitors of oncogenic drivers other than ERBB2 is due to the complex genomic architecture of EAC, with multiple putative driver alterations per tumor." (PMID 34503107, 2021). "Contrarily, non-responder tumours (HCC07-0409 and HCC29-0909A) showed large areas that are positive for p-ErbB2 or p-ErbB3, which is consistent with previous Western blot analyses." (PMID 34156519, 2021). "Immunohistochemical staining indicated that PDX tumours that did not respond to infigratinib highly and uniformly express EZH2, p-ErbB2, and/or p-ErbB3." (PMID 34156519, 2021). "Altogether, in biodistribution and toxicity analyses, ERBB2-CAR CIK cells were safe, well-tolerated, and effective, especially in the model with low tumor burden, which was not likewise observed for WT CIK cells." (PMID 33193388, 2020). "Of note, ERBB2-CAR CIK cells, but not WT CIK cells were detectable by PCR at tumor sites, albeit at lower levels compared to preemptive ERBB2-CAR CIK cell therapy." (PMID 33193388, 2020). "MEDICA inhibited the viability of ErbB2 tumor cells, colonies, and spheroids, while no resistance to MEDICA was observed in ErbB2 cells subjected to prolonged continuous culturing with MEDICA." (PMID 32695336, 2020). "The two alterations, however, seem to influence the tumor phenotype independently, as supported by finding that ~50% of the EPN3-amplified cases do not show ERBB2 amplification." (PMID 32541686, 2020).